TEX13D (TEX13 family member D)
Gene: Protein-coding gene on chromosome X (124,246,249 to 124,336,863, forward strand). Ensembl gene ENSG00000282419.
Homologues: Orthologues: chimpanzee TEX13D (97% identical), macaque TEX13D (72% identical), dog TEX13D (48% identical), mouse Tex13d (32% identical), rat LOC134484021 (32% identical), rat Tex13c (30% identical), mouse Tex13c1 (28% identical), Drosophila melanogaster CG14718 (8% identical). Paralogues in human: TEX13C (48% identical), TEX13A (15% identical), TEX13B (11% identical).